VRK1 (VRK serine/threonine kinase 1)
Diseases named in the same sentence as VRK1 in open-access papers (continued):
Sharing a sentence is not in itself a finding about the gene and the disease.
cancer (continued). "In summary, by integrating genome-wide, loss-of-function genetic screens with RNA sequencing and DNA methylation, we identified VRK1 as a selective vulnerability in CNS and PNS cancers with low VRK2 expression." (PMID 36040810, 2022). "In contrast, VRK1 expression was negatively related to the HSC and NKT in most TCGA cancers." (PMID 38157278, 2023). "Subsequently, the correlation between VRK1 and TMB was observed in 18 types of cancer." (PMID 38157278, 2023). "However, to date, no study has analyzed the role of VRK1 in pan-cancer analysis." (PMID 38157278, 2023). "However, until now, the regulation of VRK1 gene expression has not been studied in cancer." (PMID 34071140, 2021).
infection (7 papers, 2009 to 2026). The state of being infected such as from the introduction of a foreign agent such as serum, vaccine, antigenic substance or organism. "Overall, the combination of both the marker rescue assay and cellular transgene complementation assay provide evidence that the D156A mutant is a nonrepressive B12 variant, strongly indicating that complex formation between VRK1 and B12 is connected to B12 function during ΔB1 infection." (PMID 35543552, 2022). "Whereas VRK1-ΔNLSΔBasic is predominantly cytoplasmic in uninfected cells, this mutant shifted partially to the membrane-associated and soluble nuclear fractions upon WTeHAB12 infection (compare lanes 1 to 3 to lanes 5 to 7)." (PMID 35543552, 2022). "Previous studies indicate that B12 impacts the poxviral life cycle via association with VRK1, a cellular kinase with which B12 copurifies and may redirect to the nucleus during infection." (PMID 35543552, 2022). "Recently, it was discovered that early in infection the vaccinia virus (VACV) B12 pseudokinase copurifies with the cellular kinase VRK1, a proviral factor, in the nucleus." (PMID 35543552, 2022). "Only 30 to 50% of VRK1 remained soluble during WT infection, whereas in uninfected or mutB12-infected cells, 95 to 100% of VRK1 was soluble (bottom left)." (PMID 35543552, 2022). "Strikingly, the decrease in VRK1 solubility during WT infection was lost with mutB12 infection (compare lanes 4 and 6)." (PMID 35543552, 2022). "Similar to the CV1 cells, in uninfected HAP1 cells, VRK1 was found predominantly in the soluble nuclear fraction (lanes 3 and 4), while WT infection results in less VRK1 detection in the soluble nuclear fractionation and greater detection in the chromatin-associated nuclear fraction (lanes 7 and 8)." (PMID 35543552, 2022). "Interestingly, we identify a point mutation of B12 capable of abrogating interaction with VRK1 and which renders B12 nonrepressive during infection." (PMID 35543552, 2022). "Particularly, in vivo expression of PDR802, SRE1, VRK1, PKH201, and YFH701 was strongly induced in all infected tissues tested during almost all infection stages." (PMID 32251295, 2020). "To further examine the impact of VRK1 on B12 localization, we compared the localization of HA-B12 during infection using cells lacking VRK1 (VRK1KO-CTRL) or cells expressing either nuclear VRK1 (VRK1KO-VRK1 WT) or cytoplasmic VRK1 (VRK1KO-VRK1 ΔNLSΔBasic)." (PMID 35543552, 2022). "However, unlike WT VRK1, infection was not sufficient to relocalize VRK1-ΔNLSΔBasic to the chromatin fraction under these conditions (compare lanes 8 and 12)." (PMID 35543552, 2022).
neurological diseases (5 papers, 2018 to 2024). "Rare variants of the human VRK1 gene are associated with a heterogeneous group of neurological diseases, affecting motor neurons and the peripheral nerves, sensory and sensory-motor." (PMID 38554151, 2024). "These pathogenic VRK1 variants associated with neurological diseases cause an altered assembly of Cajal bodies, and some also have an altered action potential." (PMID 38753965, 2024). "An additional implication regarding the role of VRK1 in the response to oxidative stress is its potential pathogenic role in severe neurological diseases." (PMID 38732093, 2024). "Bi-allelic VRK1 variants, either homozygous or compound heterozygous, are responsible for a heterogenous group of neurological diseases affecting motor neurons and the peripheral nerves, indicating that the alteration of both alleles is required." (PMID 38554151, 2024). "The functional variability of VRK1 protein variants and their different combinations are a likely contributor to the clinical phenotypic heterogeneity of motor neuron and neurological diseases associated with rare VRK1 pathogenic variants." (PMID 38554151, 2024). "Recessive inherited mutations in the gene encoding Vaccinia-related kinase 1 (VRK1), a serine-threonine kinase involved in cell cycle regulation and the DNA damage response, result in a neurological disease that has both developmental and degenerative manifestations." (PMID 30050127, 2018).
adenocarcinoma (2 papers, 2011 to 2016). A common cancer characterized by the presence of malignant glandular cells. "Gene-expression analysis in adenocarcinomas based on microarray data showed that VRK1 was correlated with members of the mitotic cell-cycle gene network, including CENP-A, CENP-K, CENP-N, CENP-Q, Bub1, BubR1, SMC2, and CAP-G." (PMID 27231315, 2016).
neurodegenerative disease (1 paper, 2020). A disorder of the central nervous system characterized by gradual and progressive loss of neural tissue and neurologic function. "Known mutation of the VRK1 gene, p.W375X, which has been linked to development of neurodegenerative disease in human, truncates a C-terminal peptide of the VRK1 molecule that bears Ser376 and Thr386." (PMID 32266931, 2020).
VRK1 also shares sentences with these, for which no sentence is quoted: Intellectual disability (3 papers); distal hereditary motor neuropathies (2); leukemia (2); melanoma (2); neurodevelopmental disorder (2); rhabdomyosarcoma (2); anaplastic astrocytoma (1); arthrogryposis (1); brain malformations (1); Cerebellar atrophy (1); Cerebellar cyst (1); Coffin-Lowry syndrome (1); colon cancer (1); developmental delay (1); ductal breast carcinoma in situ (1); esophageal cancer (1); Fanconi anemia (1); Fanconi anemia complementation group A (1); gynecological cancers (1); hereditary spastic paraplegia (1); juvenile ALS (1); Leigh syndrome (1); multiple myeloma (1); muscular atrophy (1); optic atrophy (1); ovarian carcinoma (1); pancreatic cancer (1); peripheral nerve disorders (1); pontocerebellar hypoplasia (1); Respiratory insufficiency (1).
A further 3 diseases each share a sentence with VRK1 in 1 paper.